THBS1 (thrombospondin 1)
Diseases named in the same sentence as THBS1 in open-access papers (continued):
Sharing a sentence is not in itself a finding about the gene and the disease.
tumor (continued). "THBS1 can affect tumor cell function through interactions with cell surface receptors." (PMID 40988744, 2025). "The observed decrease in THBS1 expression following TTFields exposure may therefore reflect a complex regulatory shift that not only affects clot architecture, but also modulates tumor–stroma communication and stress adaptation." (PMID 40885689, 2025). "Furthermore, studies suggest that THBS1 supports the adhesion and migration of tumor cells in vitro." (PMID 41438033, 2025). "There was a significant enhancement in the H2-K1 signaling pathway and a notable weakening of the THBS-1 signaling pathway between tumor cells and CD8+T cells following RBMX knockout; the expression of H2-K1 in tumor cells significantly increased, while the THBS-1 expression was decreased." (PMID 40941025, 2025). "It is thought that, in contrast to epithelial markers, such as plakoglobin or cytokeratins 18 and 19, mesenchymal markers, TIMP-2, TIMP-3, thrombospondin-1 and/or α1VI/α2I integrins may predict the invasive and metastatic phenotype of tumour cells." (PMID 40724562, 2025). "RNA-based microarray analysis of GBM cells confirmed coagulation-related changes, including upregulation of platelet adhesion marker ITGA2, and downregulation of THBS1, a regulator of clotting, platelet aggregation, extracellular matrix remodeling, and tumor invasiveness." (PMID 40885689, 2025). "Remarkably, the paper currently being reviewed and discussed is one of the few articles regarding M1-like phenotypic tumor-activator, which reported M1-like TAMs activated by exosome-transferred THBS1 promote malignant behaviors cascading a mesenchymal/stem-like phenotype of OSCC." (PMID 39113068, 2024). "Increased THBS1 facilitated tumour cell invasion and metastasis." (PMID 38778448, 2024). "THBS1, a tumor-specific extracellular matrix protein and tumor suppressor, is known to inhibit angiogenesis, regulate anti-tumor immunity, and stimulate tumor cell migration in the tumor microenvironment." (PMID 38183097, 2024). "THBS1, THBS2, and PEDF reduce angiogenesis and promote tumor-associated lymph angiogenesis in iCCA." (PMID 39040110, 2024). "This underscores THBS1 as an important target for tumor therapy, deserving further exploration." (PMID 38183097, 2024). "In GC, THBS1 could have a proangiogenic effect, and its elevated expression correlates with tumor growth and lymph node metastasis." (PMID 39456895, 2024). "THBS1, a matricellular protein, is strongly expressed during inflammation and plays roles in inducing macrophage IL-10 production, inhibiting angiogenesis, modulating immune responses, and affecting tumor development." (PMID 39453208, 2024). "THBS1 plays a crucial role in suppressing tumor growth, cell migration, and angiogenesis." (PMID 39275122, 2024). "THBS1 promotes tumour cell invasion and growth, and its knockdown inhibits cancer growth." (PMID 38000389, 2024). "The administration of CTTPPPD may increase THBS1 expression, leading to the inhibition of tumor growth and metastasis, thereby improving treatment outcomes." (PMID 39275122, 2024). "Interestingly, we identified THBS1, which fulfills a multitude of functions in the tumor microenvironment, including immunity and chemotherapy resistance, as a potent factor regulating the motility phenotype of CAFs." (PMID 36868311, 2023). "We identified thrombospondin-1 (THBS1), associated with the most aggressive and invasive GBM tumors, as one of the most highly downregulated G⍺12 dependent genes in the tumor samples analyzed by DESeq2, demonstrating that THBS1 expression was decreased by 90% in G⍺12 KD tumors." (PMID 38104152, 2023). "Consequently, we provided evidence that THBS1 was expressed in the TS, despite the presence of tumor tissue, which was consistent with the results of ST." (PMID 37124494, 2023).
tumor (continued). "Furthermore, expression of BZW2 positively correlates with T cell-mediated immunity to tumor cells and Th2 cells, and THBS1 can reduce the permeability of human dermal microvascular endothelial cells (HDMECs)." (PMID 37122373, 2023). "Thrombospondin 1 (THBS1), a tumour suppressor, was identified as the target gene of METTL14." (PMID 37284313, 2023). "We hypothesized that Kaiso is involved in immune evasion and thereby in tumor growth by modulating the THBS1/CD47/SIRPA axis." (PMID 37190208, 2023). "The overall effect is to promote tumor progression, as M1-like macrophages could cascade a stem-like phenotype of tumor cells via the IL6/Stat3/THBS1 feedback loop." (PMID 36614179, 2023). "In addition, THBS1 functions as a positive modulator of innate anti-tumor immunity by attracting M1 macrophages to the sites of inflammation or injury and stimulating reactive oxygen species (ROS)-mediated tumor cytotoxicity." (PMID 37190208, 2023). "Our finding that THBS1 knockdown phenocopies that of G⍺12, with little effect on tumor size but a clear change in invasiveness at the tumor border, suggests that upregulation of THBS1 through G⍺12 signaling is one of the transcriptional targets that mediate GBM tumor invasiveness." (PMID 38104152, 2023). "Furthermore, in the tumor tissue, the upregulated ligand-receptor pairs mostly existed in the macrophage-macrophage communication including Thbs1-, Spp1-, Lgals9-, and Csf-related pairs, which were highly related to immunity suppression." (PMID 36718369, 2023). "On the other hand, THBS1 plays a role in certain pathways that promote tumour development." (PMID 37783703, 2023). "Furthermore, RNA velocity predicted that tumor-specific SPP1+ macrophages probably originated from THBS1+ macrophages." (PMID 35365629, 2022). "Interestingly, thrombospondin-1 has emerged as a potential regulator of the TME that would play a role in tumor vessel growth and function, as well as in escape from innate and adaptive antitumor immunity." (PMID 35565321, 2022). "Therefore, they used 3TSR (Thrombospondin-1 three-type 1 repeat, collectively referred to as 3TSR) to induce tumor regression and normalize tumor vasculature before administration of oncolytic NDV." (PMID 36424577, 2022). "Indeed, a study using a model for inflammation-induced colon carcinogenesis (azoxymethane [AOM]/dextran sulphate sodium [DSS]) in Thbs1-/- mice showed a fivefold reduction in tumour burden, suggesting a role for THBS1 in tumour progression." (PMID 35543624, 2022). "Our observations from this study suggest that FN1 and THBS1 might have potential to serve as novel biomarkers for predicting NSCLC tumor response to radiotherapy." (PMID 36567906, 2022). "THBS1 is an anti-oncogene which plays an essential role in the tumor microenvironment." (PMID 35984577, 2022). "Although THBS1 is not usually mutated in most cancers, its expression is regulated by multiple tumour suppressor genes and oncogenes, making it a major carcinogenic player." (PMID 36354023, 2022). "Collectively, these results point out that THBS1 may act as a potential tumor suppressor to suppress PCa proliferation." (PMID 35354789, 2022). "Previous findings suggested that BMP4 could upregulate THBS1 expression and BMP4/THBS1 loop suppress tumor angiogenesis." (PMID 36145624, 2022). "FN1, APOA1, CXCL8, MMP1, MMP3, and THBS1 were significantly upregulated in the tumor samples." (PMID 35719376, 2022). "METTL14 promotes tumor progression by binding to THBS1 3’ UTR region and decreasing its expression." (PMID 35354789, 2022). "Additionally, THBS1, as a tumor suppressor inhibiting PCa proliferation, can be considered as the potential therapeutic target in the future." (PMID 35354789, 2022). "THBS1 inhibits tumor cell growth by activating TGFβ in TGFβ-responsive tumor cells." (PMID 35409214, 2022).
tumor (continued). "The results showed significantly elevated proteins levels such as thrombospondin-1 (TSP1), vascular endothelial growth factor (VEGF), and protein-lysine 6-oxidase (LOX), which have been well documented to be associated with tumor progression, angiogenesis, and treatment resistance." (PMID 35812406, 2022). "Nevertheless, in a subset of subjects, there was an increase in CA accumulation during GEM treatment, possibly related to low dosage (i.e., metronomic) delivery, which has previously been reported to normalize tumor vasculature by increased levels of the angiogenesis inhibitor thrombospondin-1." (PMID 36074156, 2022). "Previous studies have reported that THBS1 promotes tumor metastasis by enhancing EMT." (PMID 34804159, 2021). "The correlation analysis revealed that THBS1 methylation in PPLF was positively correlated with THBS1 methylation in tumor tissue (γ = 0.9673, p < 0.0001) and THBS1 methylation in serum was also positively correlated with methylation in the tumor tissue (γ = 0.9521, p < 0.0001)." (PMID 34390026, 2021). "Indeed, loss of LIFR down-regulated dormancy-related genes (e.g., thrombospondin-1 (TSP1), tropomyosin-1 (TPM1), TGF-ß2) and resulted in tumor cell dissemination to bone and osteolytic disease in vivo." (PMID 33809315, 2021). "It has been shown that miR-204-5p promotes tumor angiogenesis through regulation of thrombospondin 1 and similar mechanisms could be at play in the regulation of lymphangiogenesis." (PMID 34316330, 2021). "Decreased thrombospondin-1 mRNA and protein expression are associated with progression in several cancers, while expression by nonmalignant cells in the tumor microenvironment and circulating levels in cancer patients can be elevated." (PMID 33925464, 2021). "Similarly, using immunofluorescence analysis on tumor slices, we showed that the amount of THBS1 protein was significantly enhanced in Stau1-KD tumors compared to control tumors." (PMID 35008641, 2021). "These proteins (THBS1, FBLN1, EDIL3, QSOX1, ACTN4, MMP3) also displayed differential mRNA expression in CRC compared to healthy intestine in the CRC TCGA dataset, and are implicated in tumour growth and metastasis regulation." (PMID 33802764, 2021). "THBS1 plays a complex role in tumor development and progression." (PMID 34804159, 2021). "Additionally, we found that Thsb1 (Thrombospondin-1) expression in residual tumor cells in both the HER2/neu and Wnt1 models was elevated ~ 3-fold compared to primary or recurrent tumor cells (p values < 0.01)." (PMID 34088357, 2021). "In addition to regulating angiogenesis and perfusion of the tumor vasculature, thrombospondin-1 limits antitumor immunity by CD47-dependent regulation of innate and adaptive immune cells." (PMID 33925464, 2021). "Additionally, inhibition of THBS1 by miR-194 promoted angiogenesis and tumor growth of colonic carcinoma xenografts." (PMID 34502094, 2021). "Thus, lumican was able to modulate the response of a therapeutic peptide targeting the extracellular matrix by specific inhibition of thrombospondin-1, playing a substantial role in maintaining tumor microenvironment integrity." (PMID 32548117, 2020). "One of the major mechanisms by which thrombospondin-1 regulates tumor outgrowth and dormancy is by interacting with the latency associated peptide in complex with TGFβ to release TGFβ into the local environment and thereby stimulate TGFβ signaling (see Tenascin-C above)." (PMID 33014869, 2020). "It has an antiangiogenic effect on the tumor vascular system, which may be mediated by increasing the level of endogenous angiogenesis inhibitor thrombospondin-1 (TSP-1)." (PMID 33343807, 2020). "This may, however, point to a larger genetic dependency for the role of thrombospondin-1 in tumor progression." (PMID 33014869, 2020). "In addition, THBS1 can also affect tumor cell adhesion, invasion, migration, proliferation, apoptosis, and immune evasion." (PMID 32874785, 2020).
tumor (continued). "Thrombospondin-1 (TSP1) represents a classic example of a glycoprotein in the tumor microenvironment and is commonly recognized for its anti-angiogenic functions and impact on tumor cell invasion via multiple cell surface molecules and matrix metalloproteinase interactions." (PMID 31418125, 2019). "Taken together, these data indicate that THBS1 has a role in both tumour expansion and invasion." (PMID 30850588, 2019). "THBS1 may induce angiogenesis in tumors, influence tumor cell adhesion, migration, invasion, and metastasis both in vitro and in vivo." (PMID 31580518, 2019). "Moreover, silencing of BZRAP1-AS1 repressed the angiogenesis as well as the tumor growth of HCC in vivo via up-regulating THBS1." (PMID 31847842, 2019). "THBS1 regulates the matrix‐metalloproteinases (MMPs) 2 and 9, which could be essential for tumor progression." (PMID 31580518, 2019). "Since THBS1 is a matricellular protein with a plethora of regulatory functions, we set out to further elucidate its role through a systematic analysis using multiple cell models and assays with a focus on tumour cell invasion." (PMID 30850588, 2019). "More importantly, overexpression of RRM2 in gastric cancer cells promotes their invasiveness by regulating the AKT/NF-κB signaling pathway, and RRM2 increases tumor angiogenesis and growth by modulating the expression of thrombospondin-1 (TSP-1) and vascular endothelial growth factor (VEGF)." (PMID 31696057, 2019). "THBS1 may not only act in the angiogenic core of the tumour but also in areas of tumour cell invasion." (PMID 30850588, 2019). "On the contrary, THBS1 was under-expressed in primary tumor." (PMID 31412643, 2019). "In this analysis, THBS1 was the gene with the highest connectivity in the peripheral tumour areas." (PMID 30850588, 2019). "The results show that knockdown of CD47 significantly impairs THBS1-induced tumour cell invasion." (PMID 30850588, 2019). "In recent years, THBS1, as a tumor suppressor gene, had gradually attracted people's attention, which could influence the growth of tumors by inhibiting angiogenesis and activating the transforming growth factor." (PMID 32117788, 2019). "THBS1 upregulation together with the impaired migration of endothelial cells might be the mechanisms how GPx4 inhibits tumor angiogenesis." (PMID 29515790, 2018). "Whereas, tumour associated immune cells (TAMS), tumour associated fibroblasts (e.g., FAP, α-SMA, FGFRs, tenascin-C and thrombospondin-1) and tumour initiating stem cells (e.g., CD133, EpCAM and aldehyde dehydrogenases), have been utilised to allow for NPPSs drug targeting within a TME." (PMID 30322132, 2018). "Thrombospondin-1 may potentiate tumor progression, promotes tumor cell adhesion, migration and invasion." (PMID 29855483, 2018). "It interacts with a variety of ECM molecules and cell surface receptors and this protein has been shown to play roles in tumorigenesis; particularly, it was showed that THBS1 induced cell migration in several tumor cell lines suggesting that THBS1 is involved in cancer invasion." (PMID 29113313, 2017). "Increasing the expression levels of THBS1 or THBS2 in tumor tissue can inhibit tumor growth." (PMID 29190912, 2017). "However, after 1–2 cycles of chemotherapy, patients who had PLN involvement at surgery showed significant up-regulation of tumor THBS1, TNC, FN, SPARC and α-SMA expression." (PMID 27487140, 2016). "In particular, we observed that SAHA treatment could significantly reduce the percentages of tumor cells with positive staining of THBS1, Nestin, N-cadherin, SNAIL/SLUG, Vimentin and b-catenin." (PMID 27634890, 2016).
tumor (continued). "Although the role of THBS1 in regulating tumor progression was controversial, in invasive cancer, THBS1 may function as an adhesive protein or a modulator of extracellular proteases to promote tumor invasion." (PMID 27487140, 2016). "Of note, while TGFB1, a master regulator of the malignant phenotype, appeared to be mostly up-regulated in the tumour, its activators THBS1, FN1 and ITGA4 were strongly induced in tumor cells and ECs, highlighting a concerted molecular interaction to regulate cellular activity." (PMID 27049916, 2016). "ECs of intermediate tumours showed weak positivity for Thbs1." (PMID 27049916, 2016). "THBS1 protein was located in tumor cells and was undetectable in stroma." (PMID 25051363, 2014). "In an early stage, high stromal expression of THBS1 inhibits tumor growth whereas later in the vascularized tumor THBS1 may increase the adhesive properties of tumor cells or modulate extracellular matrix proteins thereby promoting tumor invasion." (PMID 24528603, 2014). "Since THBS1 was found to be characteristically hypermethylated in CCSK, we next examined whether the hypermethylation of THBS1 alone can distinguish CCSK from other tumor groups." (PMID 23638012, 2013). "THBS1 is another protein increased in MDSCs from the 4T1 tumor-bearing host." (PMID 21853032, 2011). "However in cancer cells when thrombospondin-1, endostatin, and tumstatin are over expressed, tumor cells were found to escape angiogenesis inhibition by up-regulation of various proangiogenic factors." (PMID 22267953, 2011). "THBS1 suppresses tumor growth by activating TGF-β and by inhibiting angiogenesis." (PMID 20573232, 2010). "Mouse experiments also showed that altered TGF-β1 was associated with the latent TGF-β1 binding proteins that can cause inflammation and tumors and that the disrupted TGF-β1 pathway can lead to tumor growth by increasing the tumor angiogenesis induced by decreased expression of thrombospondin-1." (PMID 19566948, 2009). "However, some of the genes exclusively regulated in A549 such as Integrin αV, thrombospondin 1, α2macroglobulin have been shown to aid tumour survival, maintenance and metastasis." (PMID 17425807, 2007). "In addition, we found a strong prognostic impact of angiogenesis as estimated by microvessel density (MVD), as well as significant influence of thrombospondin-1 (TSP-1) staining in the tumour stroma." (PMID 16189525, 2005). "Furthermore, tumour cell thrombospondin-1 promoted tumour cell invasion and decreased tumour cell adhesion through up-regulation of urokinase plasminogen activator receptor-controlled urokinase plasminogen activator and plasmin activities." (PMID 10917542, 2000). "We conclude that tumour cell-produced thrombospondin-1 may play a critical role in the regulation of tumour cell adhesion and tumour cell invasion." (PMID 10917542, 2000). "THBS1 drives the development of various skin diseases at the molecular level by modulating core pathological processes, such as angiogenesis, fibrosis, inflammation, and tumor progression, thereby serving as a pivotal nexus between fundamental research and clinical dermatology." (PMID 41930128, 2026). "Similarly, thrombospondin 1 derived from salivary exosomes of OSCC cells appears to contribute to the polarization of macrophages toward an M1-like tumor-associated phenotype and provoke the extensive invasion of tumor cells." (PMID 40723410, 2025). "Thus, in the context of combination treatment, arsenic sulfide inhibits THBS1 in tumor cells while upregulating CD69 and downregulating LAG3 in T cells, it is reasonable to surmise that arsenic sulfide modulates T cell activity to augment the efficacy of anti-PD-1 therapy." (PMID 41019041, 2025). "Another study applied disease pathways analysis and found that the proteins Thbs1 (or TSP-1), KNG1, Histidine-rich glycoprotein (HRG), and F9, F10, and F12 were upregulated in HPV+ variant P16-induced oropharyngeal tumours compared to non-P16 variant HPV+ tumours." (PMID 41462954, 2025).